NDRG1 (N-myc downstream regulated 1)
Diseases named in the same sentence as NDRG1 in open-access papers (continued):
Sharing a sentence is not in itself a finding about the gene and the disease.
hepatocellular carcinoma (continued). "Paradoxically, another study demonstrated that NDRG1 phosphorylation at Thr346 in hepatocellular carcinoma cells promotes its pro-oncogenic role and showed that phosphorylated NDRG1 (p-NDRG1) at Ser330 mainly localizes in the nucleus, while p-NDRG1 at Thr346 is predominantly found in the cytoplasm." (PMID 38983911, 2024). "Although NDRG1 is primarily recognized for its anti-oncogenic and anti-metastatic functions, studies have revealed its pro-oncogenic role in certain cancers like gastric cancer and hepatocellular carcinoma." (PMID 39199357, 2024). "NDRG1 was highly expressed in hepatocellular carcinoma cells, macrophages and NK cells." (PMID 37517087, 2023). "However, a number of studies have also demonstrated a pro-tumourigenic role for NDRG1, particularly in hepatocellular carcinoma." (PMID 37345116, 2023). "Finally, we analyzed the correlation between these transcription factors and stemness-related genes in hepatocellular carcinoma transcriptome data and found a significant correlation between NDRG1 and these transcription factors compared to LPCAT1." (PMID 37717019, 2023). "However, NDRG1 also plays an oncogenic role in certain cancer types, including scirrhous gastric cancer and hepatocellular carcinoma, indicating that it performs pleiotropic functions depending on the cancer type." (PMID 34077484, 2021). "However, compared with normal tissue, NDRG1 expression was shown to be upregulated in homologous hepatocellular carcinoma and oral squamous cell carcinoma." (PMID 31443698, 2019). "However, in contrast, some studies have demonstrated that NDRG1 promotes cell migration and invasion in hepatocellular carcinoma." (PMID 26418878, 2015). "In hepatocellular carcinoma (HCC), H2B-K58 lactylation at the NDRG1 locus links the activity of LDHA to epigenetic control, creating a feedback loop that supports senescence-resistant clones." (PMID 41373440, 2025). "In hepatocellular carcinoma (HCC), NDRG1 suppression is correlated with the activation of a senescence-associated signalling pathway." (PMID 40332138, 2025). "A recent research on the microenvironment development of hepatocellular carcinoma (HCC) illustrated NDRG1 increase in HCC tissues, which cooperated with FOXQ1 to promote hepatic stellate cells recruitment." (PMID 34965023, 2021). "They showed the decrease on Hepatocellular Carcinoma Cell (HCC) invasion in normoxic and hypoxic conditions and showed that fucoidan suppressed cells proliferation and invasion in a NDRG-1/CAP43-dependent manner." (PMID 27763505, 2016). "In hepatocellular carcinoma (HCC), histone H2B can be Kla-modified at K58, thus facilitating the transcription of NDRG1 to inhibit cell senescence and apoptosis." (PMID 41285721, 2025). "In bladder cancer cells, ectopically upregulating NDRG1 decreased cells proliferation and invasion in a GDF15-dependent manner, while in hepatocellular carcinoma, LINC01419 promotes cell proliferation and metastasis by enhancing NDRG1 promoter activity." (PMID 38271137, 2024). "We also found that the expression of NDRG1, NPM1, TXNRD1 in the hepatocellular carcinoma samples from patients with poor prognosis were higher than the samples from patients with better prognosis." (PMID 38097352, 2023). "Compared with the paracellular tissues, the expression of NDRG1, NPM1, TXNRD1 were both increased in the hepatocellular carcinoma samples." (PMID 38097352, 2023). "Consistently, it has been found that hypoxia-related genes CA9, NDRG1, SLC2A1, P4HA1 and ENO1 induced EMT in hepatocellular carcinoma, bladder cancer, laryngeal cancer and gastric cancer, respectively." (PMID 34136390, 2021). "In addition, CAFs induce forkhead box Q1 (FOXQ1) expression; as a result, N-myc downstream-regulated gene 1 (NDRG1) is trans-activated to enhance hepatocellular carcinoma (HCC) initiation." (PMID 30380628, 2018).
hepatocellular carcinoma (continued). "In contrast, the levels of Thr346 phosphorylation did not change in HepG2 and Hep3B hepatocellular carcinoma cells, where a pro-oncogenic effect of NDRG1 was evident." (PMID 40378957, 2025). "However, NDRG1 is found to be highly expressed in HCC, and promotes hepatocellular carcinoma proliferation and metastasis." (PMID 36712870, 2022). "In addition to NDRG1, Wang and colleagues demonstrated that the NDRG1-inducer Dp44mT also up-regulated NDRG2, with the inhibition of MMP-2 activity being demonstrated in hepatocellular carcinoma cells." (PMID 32948029, 2020). "However, the cellular function of NDRG1 remains elusive in human hepatocellular carcinoma (HCC)." (PMID 24260043, 2013). "For example, the NDRG1 protein was significantly overexpressed in human hepatocellular carcinoma (HCC) samples relative to its expression in non-tumour liver samples or cirrhotic and benign liver lesion samples, and this overexpression was associated with vascular invasion and poor survival." (PMID 30914736, 2019).
colorectal cancer (38 papers, 2006 to 2025). A primary or metastatic malignant neoplasm that affects the colon or rectum. "Previous studies indicated that the decreased NDRG1 expression was independent unfavorable prognostic factors for survival of patients with high risk stage II colorectal cancer." (PMID 23874544, 2013). "In a retrospective analysis, high levels of NDRG1 was associated with indolent tumour growth and with improved survival in patients diagnosed with colorectal cancer." (PMID 16832411, 2006). "Although few studies have shown that NDRG1 expression may be associated with less aggressive colorectal cancer, association between NDRG1 and prognostic features in rectal cancer remained unknown." (PMID 29801473, 2018). "In colorectal cancer, NDRG1 expression was suggested to transition from the membrane to the cell nucleus, which was associated with lymph node metastasis." (PMID 37858101, 2023). "The role of NDRG1 has been vastly assessed in the contexts of breast, prostate, gastric and colorectal cancers." (PMID 37249826, 2023). "After verifying the transfection effect, we demonstrated that comparing to the cells overexpressing PKCδ, the invasion and migration ability decreased in co-overexpression of PKCδ and NDRG1 colorectal cancer cells." (PMID 36816970, 2023). "Recently, it has been shown that MORC2 promotes the development of an aggressive colorectal cancer phenotype through inhibition of NDRG1." (PMID 36234785, 2022). "In previous studies, NDRG1 inhibited the NF-κΒ signaling pathway, which attenuated E-cadherin expression in pancreatic and colorectal cancers." (PMID 36293154, 2022). "In colorectal cancer patients with lymph node metastases, the nuclear localization of NDRG1 was significantly higher in the neoplasm tissue than in the normal mucosa." (PMID 35563887, 2022). "Our study provides evidence illustrating that CLDN2 promotes colorectal cancer progression by suppressing NDRG1 expression via stabilising CLDN2/ZO1/ZONAB complex." (PMID 34965023, 2021). "The result that NDRG1 inhibits colorectal cancer cell proliferation and migration/invasion, partially provides evidence to support the involvement of NDRG1 in CLDN2‐mediated colorectal cancer progression." (PMID 34965023, 2021). "On account of their well-characterized roles in cancer, we investigated the mechanism of actin filament reorganization in colorectal cancer cells in an NDRG1-modified manner." (PMID 33994856, 2021). "This study sheds light on the first mechanistic insight into CLDN2‐regulated NDRG1 expression in colorectal cancer." (PMID 34965023, 2021). "The mRNA levels of NDRG1 in the same GEO Profiles (GDS2947) indicated significantly decreased expression of NDRG1 in colorectal cancers." (PMID 34965023, 2021). "Here we provided in silico evidence that NDRG1 plays a crucial role in actin reorganization in colorectal cancer (CRC)." (PMID 33994856, 2021). "N-myc downstream-regulated gene 1 (NDRG1) inhibits colorectal cancer cell proliferation through emulatively antagonizing NEDD4-mediated ubiquitylation of p21, which suggests an oncogenic role of NEDD4 in colorectal cancer." (PMID 33767993, 2021). "NDRG1 has been reported as a tumor suppressor decreasing in colorectal cancer inhibits tumor proliferation through increasing p21 stability." (PMID 33023006, 2020). "Immunohistochemistry (IHC) was used to detect NDRG1 and p21 protein expression in colorectal cancer tissue, and clinical significance of NDRG1 was also analyzed." (PMID 31831018, 2019). "On the other hands, the protein expression of NDRG1 in colorectal cancer was medium to high (8th out of 20 organs tested)." (PMID 29801473, 2018). "The purpose of this study was to investigate the role of NDRG1 in the apoptosis of colorectal cancer (CRC) cells." (PMID 28537875, 2017). "To determine the role of NDRG1 in human colorectal cancer development, we first evaluated mRNA expression levels in 20 pairs of cancer specimens randomly selected from the cohort." (PMID 29137287, 2017).
colorectal cancer (continued). "NDRG1 over-expression promoted apoptosis in colorectal cancer cells whereas depletion of NDRG1 resulted in resistance to oxaliplatin treatment." (PMID 28537875, 2017). "The aim of this study was to evaluate the clinical significance of N-myc downstream-regulated gene 1 (NDRG1) in colorectal cancer (CRC) patients and to explore the mechanisms governing the role of NDRG1 in apoptosis of CRC cells." (PMID 29137287, 2017). "Then, the effects of over-expression and depletion of NDRG1 gene on apoptosis of colorectal cancer were tested in vitro and in vivo." (PMID 28537875, 2017). "NDRG1 expression has been shown to be significantly lower in cancer tissue compared with adjacent normal tissue; moreover, NDRG1 expression has been shown to be inversely correlated with the metastasis of some cancers, such as prostate and colorectal cancer." (PMID 26965928, 2016). "N-myc downstream-regulated gene 1 (NDRG1), has been identified as an important metastasis suppressor for colorectal cancer (CRC)." (PMID 26418878, 2015). "Herein, we deciphered a novel mechanism by which NDRG1 mediates its inhibitory functions on cancer cell migration in prostate and colorectal cancer cells." (PMID 25860930, 2015). "Although NDRG1 has been defined as a metastasis suppressor gene, it is of interest that NDRG1 mRNA expression was found to be up-regulated in colorectal cancer data from the Cancer Genome Atlas (TCGA)." (PMID 26418878, 2015). "Several investigations have been reported referring to the detailed mechanisms of NDRG1 in inhibiting colorectal cancer migration, invasion and metastasis in vitro." (PMID 23874544, 2013). "Accumulating evidence has demonstrated NDRG1 to be a metastasis suppressor in colorectal cancer." (PMID 38891773, 2024). "Our research group has studied NDRG1 for a long time and found that the downstream mechanism of NDRG1 inhibiting colorectal cancer metastasis may involve multiple signaling pathways." (PMID 36816970, 2023). "Furthermore, MORC2–SIRT1 complex suppresses NDRG1 expression to encourage metastasis in colorectal cancer." (PMID 37892209, 2023). "NDRG1 is a metastasis suppressor and prognostic colorectal cancer (CRC) biomarker." (PMID 37892209, 2023). "NDRG1 may act as an oncogene, for it has been reported to be overexpressed in many types of cancers, including bladder, liver, lung, and colorectal cancers." (PMID 34307149, 2021). "In line with previously reported results, our observations indicated that NDRG1 downregulation in colorectal cancer tissue was involved in tumour initiation and progression by a train of NDRG1‐knockout and NDRG1 overexpression‐based colorectal cell function assays." (PMID 34965023, 2021). "We next investigated the potential function of NDRG1 in colorectal cancer progression." (PMID 34965023, 2021). "Since a previous study had confirmed the interaction between CLDN2, ZO1 and ZONAB, which was involved in human lung adenocarcinoma cell proliferation, we wondered if CLDN2 indirectly modulates the expression of NDRG1 by similarly interacting with ZO1/ZONAB in colorectal cancer cells." (PMID 34965023, 2021). "To further determine whether CLDN2 modulates the protein expression of NDRG1 in colorectal cancer cells, we performed immunoprecipitation assay in HCT116 cells." (PMID 34965023, 2021). "Importantly, this novel axis revealed in our study demonstrates a mechanism by which NDRG1 exerts the anti-invasion effects through remodeling the actin cytoskeleton in colorectal cancer." (PMID 33994856, 2021). "Given that the filopodium-like protrusions enable the outgrowth of cancer macrometastases at distal sites 33, we asked whether the depletion of NDRG1 could promote the peritoneal tumor macrometastases of colorectal cancer in vivo." (PMID 33994856, 2021).
colorectal cancer (continued). "Here, we found that NDRG1 enhanced the sensitivity of CTX in colorectal cancer (CRC) cell lines." (PMID 34385595, 2021). "Interestingly, NDRG1 was previously shown to be a metastasis suppressor and is highly downregulated in colorectal cancer." (PMID 33375322, 2020). "For instance, in colorectal cancer, NDRG1 counteracts EMT, thereby reducing metastatic potential." (PMID 31029158, 2019). "Since the first time NDRG1 was recognized as metastasis suppressor in colon cancer, accumulating evidences have demonstrated that NDRG1 was down-regulated in breast, prostate, pancreatic, and colorectal cancers, showing anti-tumor and anti-metastatic functions of NDRG1." (PMID 31831018, 2019). "Our study could fulfill potential mechanisms of the NDRG1 during tumorigenesis and metastasis, which may serve as a tumor suppressor and potential target for new therapies in human colorectal cancer." (PMID 31831018, 2019). "One study showed that NDRG1 might become a tumor suppressor in colorectal cancer (CRC) by inhibiting tumor growth or inducing cell apoptosis." (PMID 30413609, 2018). "Therefore, NDRG1 is sufficient to overcome the threshold to modulate TRAIL-induced apoptosis in colorectal cancer." (PMID 29137287, 2017). "In conclusion, NDRG1 promotes oxaliplatin-triggered apoptosis in colorectal cancer." (PMID 28537875, 2017). "NDRG1 is known as a metastasis suppressor gene in prostate and colorectal cancer cell." (PMID 22844455, 2012). "However, the reliability of NDRG1 as a tumour marker is still undecided because its expression was initially shown to be repressed in colorectal cancer cells compared to the well-differentiated normal colon epithelial cells." (PMID 16832411, 2006). "Based on our prior study that revealed the correlation of NDRG1 and stress fibers assembly 9 and the discovery of the potent mechanism of NDRG1 from public datasets, here we reported a novel mechanism of NDRG1 in regulating tumor invasion by mediating actin depolymerization in colorectal cancer." (PMID 33994856, 2021). "Therefore, colorectal cancer patients can be stratified by the expression level of NDRG1." (PMID 28537875, 2017). "Phosphorylation of NDRG1 at Ser330 was demonstrated to be most pronounced in HT-29 colorectal cancer cells and PC3 prostate adenocarcinoma cells, while NDRG1 phosphorylation at Thr346 was predominantly observed in PC-3 cells and HepG2 hepatocarcinoma cells." (PMID 40378957, 2025). "A significant anticorrelation between NDRG1 and miRNA‐483‐3p expression was confirmed in the panel of 39 CCLE colorectal cancer cell lines (P = 0.043)." (PMID 36862005, 2023). "NDRG1 attenuated EMT and modulated E-cadherin expression by inhibiting caveolin-1 protein expression in colorectal cancer." (PMID 36293154, 2022). "To further clarify the functional role of NDRG1 in CRC, we first compared the NDRG1-low-expression (lower half) colorectal cancer samples with the NDRG1-high-expression (higher half) samples in silico using The Cancer Genome Atlas (TCGA)." (PMID 33994856, 2021). "To gain further insight into the manner of NDRG1 and CDC42GTP expression with clinicopathological parameters, we used tissue array containing 86 pairs of cancer and matched peritumor specimens of colorectal cancer patients." (PMID 33994856, 2021). "The correlation of NDRG1 and CDKN1A was analyzed in three colorectal cancer datasets (GSE33114, GSE4107, and TCGA)." (PMID 31831018, 2019). "NDRG1, a member of the NDRG protein family, has been shown in previous studies to have anticarcinogenic and antimetastatic effects in cancers, including breast, prostate, and colorectal cancer." (PMID 37208604, 2023). "And HSPH1 was highly expressed in different tumors, such as colorectal cancer, B-cell lymphoma, melanoma and esophageal squamous cell carcinoma, while NAA25 knockdown could upregulate IFIT2 and NDRG1 expression and downregulate HSPH1 expression." (PMID 35096568, 2021).
colorectal cancer (continued). "However, knockout of NDRG1 in HT29 and HCT116 cells elevated the proliferation ability of colorectal cancer cells." (PMID 34965023, 2021). "These indicated that NDRG1 might reduce the activity of CDC42, to regulate actin cytoskeletal dynamics in colorectal cancer cells." (PMID 33994856, 2021). "Increasing evidence suggests that over-expression of NDRG1 is able to inhibit the invasion and metastasis of CRC and has a negative correlation with colorectal cancer prognosis." (PMID 26418878, 2015).